ABCC1 (ATP binding cassette subfamily C member 1 (ABCC1 blood group))
Diseases named in the same sentence as ABCC1 in open-access papers (continued):
Sharing a sentence is not in itself a finding about the gene and the disease.
breast carcinoma (continued). "We determined the methylation patterns in tumor, tumor-adjacent and tumor-distant tissues from the same breast cancer patients in order to investigate if aberrant promoter methylation levels of ABCB1, ABCC1 and ABCG2 can be used as indicator for detection of field cancerization in breast cancer." (PMID 27689338, 2016). "In support of this hypothesis, we showed that breast cancer patients, who express high levels of Nrf2 and its downstream targets NQO1, ABCC1 and ABCC3 at the time of initial diagnosis, had poorer survival following tamoxifen therapy." (PMID 26883574, 2016). "Interestingly we observed that most of the breast cancer cell lines tested (BT-474, MCF-7, T-47D, MDA-MB-231 and HCC-1806) showed significant upregulation of ABCC1 and ABCC3 compared to immortalized cell lines (HBL-100 and MCF-10A)." (PMID 27171227, 2016). "Thus, our study revealed that similar to ABCC1, ABCC3 is also overexpressed in grade III primary breast cancers." (PMID 27171227, 2016). "Thus, we show that knockdown of ABCC1 and ABCC3 leads to reduction of stemness gene expression, and, importantly, that knockdown of ABCC3 further showed reduced breast cancer stem-like cell population." (PMID 27171227, 2016). "A recent tissue microarray study has concluded that high ABCC1 protein expression is a negative prognostic marker as it has been found in highly aggressive molecular subtypes of breast carcinoma." (PMID 25078270, 2014). "The ABCC1 transcript level was previously assessed in tumors and non-neoplastic control tissues from breast cancer patients." (PMID 25078270, 2014). "The role of ABCC1/MRP1 in the transport of tamoxifen, its metabolites or aromatase inhibitors also remains vastly unexplored and thus it is currently impossible to draw any conclusive remarks from our observations in hormonally-treated breast cancer patients." (PMID 25078270, 2014). "Very recently, we demonstrated significant overexpression of ABCC1 transcript in tumors compared to adjacent non-neoplastic tissues from breast cancer patients and suggested its intratumoral levels as potential modifiers of breast carcinoma progression." (PMID 25078270, 2014). "Another contemporary study has suggested that a high ABCC1 protein expression is a negative prognostic marker, as it has been found in highly aggressive molecular subtypes of breast carcinoma." (PMID 25078270, 2014). "Expression of ABCC1 can be regulated by methylation status that might be relevant in treatment-resistant breast cancers, potentially enabling expression changes without upstream genetic alterations." (PMID 41422323, 2025). "In summary, the miRNA-34a-5p/ABCC1 axis has positive feedback effects on the sensitivity of MCF-7 and MDA-MB-231 cells to tamoxifen and doxorubicin, respectively, which is expected to be an important target for these chemotherapies in resistant breast cancer progression future studies." (PMID 38057687, 2024). "Anticancer drug treatments lead to the activation of the PERK/eukaryotic initiation factor 2α (eIF2α)/CHOP signaling pathway in response to ER stress; when signaling does not lead to cell death, however, increased ABCC1/MRP expression has been observed in ER stress-resistant breast cancer cells." (PMID 38473345, 2024). "The main efflux transporters involved in BC MDR are ABCB1 (also termed P-glycoprotein, P-gp, or MDR1), multidrug resistance protein 1 (MRP1/ABCC1) and ABCG2 (also termed breast cancer resistance protein BCRP or mitoxantrone resistance protein MXR)." (PMID 38877575, 2024). "However, there is a lack of studies analyzing the effect of ABCC1 rs4148350 on AIC in breast cancer." (PMID 37367397, 2023). "However, our results indicated that ABCB1 rs1045642 and ABCC1 rs3743527 did not influence the development of cardiotoxicity after anthracycline-based treatment in the studied group of patients with breast cancer." (PMID 37367397, 2023).
breast carcinoma (continued). "MCF7 breast cancer cells that are thought to survive treatment with ionizing radiation (MCF-7/IR6) showed a chemoresistance phenotype by expressing high levels of MDR1 (ABCB1) but not of MRP1 (ABCC1) or BCRP (ABCG2)." (PMID 35215350, 2022). "Therefore, preliminary investigations into how ABCC1 and/or ABCC4 might elicit their effects on breast cancer cell proliferation and migration were undertaken." (PMID 33081264, 2020). "In addition, some studies point out that the up-regulation of EMT-associated transcriptional factors, containing Slug, Zeb1 and Twist1, can directly lead chemotherapy in breast cancer and NSCLC through the ATP-binding cassette (ABC) transporter family of proteins (ABCB1, ABCC1 and ABCG2)." (PMID 33282725, 2020). "However, less is known about whether ABCC1 and ABCC4 have a role in breast cancer development and/or progression." (PMID 33081264, 2020). "Moreover, we discovered that KRT19 regulates CSC reprogramming and drug sensitivity in breast cancer and cancer stem cell-like cells, through mediating stemness (NANOG, OCT4, KLF4, and SOX2) and drug-resistant (ALDH1, ABCG2, ABCC1, and ABCB1) marker expression." (PMID 29747452, 2018). "Interestingly, ABCC1 and ABCC3 knockdown cells also showed reduction in the expression of stemness genes, while ABCC3 knockdown additionally led to a reduction in the CD44high/CD24low breast cancer stem-like subpopulation." (PMID 27171227, 2016). "Our data further revealed a novel observation that identifies the knockdown of ABCC3, but not ABCC1, sensitizes breast cancer cells to methotrexate, a routinely used drug to treat breast cancers, together highlighting an important role for ABCC3 in breast cancer drug resistance." (PMID 27171227, 2016). "In the present study we aimed to enlarge the database by determining the promoter methylation patterns of ABCB1, ABCC1 and ABCG2 in cancer cell lines derived from different types of cancer, MDR cell models as well as tumor, tumor-adjacent and tumor-distant tissues from breast cancer patients." (PMID 27689338, 2016). "None of the ABCC1 SNPs showed any significant association with the clinical characteristics of BC, but the ABCC2 SNPs rs2273697 and rs717620 were found to be significantly associated with age at breast cancer diagnosis (p value = 0.042) and breastfeeding status (p value = 0.05), respectively." (PMID 31391850, 2019). "Thus, our data showed that consistent with increased doxorubicin retention, knockdown of ABCC3 also reduces the IC50 for chemotherapeutic drugs, much more than the ABCC1 knockdown, suggesting that inhibition or preventing the upregulation of ABCC3 might be efficacious for breast cancer treatment." (PMID 27171227, 2016). "Although ABCB1 and ABCC1 are two of the most studied and cancer-related ABC transporters, there is a lack of studies analyzing their effect on AIC in breast cancer." (PMID 37367397, 2023). "Balaji and colleagues examined the expression level of the ABCC1 and ABCC3 genes in breast cancer patients (without division into molecular subtypes) and assessed their role in inducing the phenomenon of resistance to anticancer drugs." (PMID 36674773, 2023). "In the present study, four SNPs of ABC transporter genes, namely ABCC1, ABCC2, ABCB1, and ABCG2, were screened in Jordanian Arabs with and without breast cancer." (PMID 31391850, 2019). "Further, CD44high/CD24low fraction, which has been identified as the stem-like cells in breast cancer, was also reduced upon knockdown of ABCC3, but not by ABCC1 knockdown." (PMID 27171227, 2016). "The present study investigated the effect of tagged haplotype of the ABCC1 gene covering NBD1 with adjacent sequences at ABCC1 transcript level in tumor and non-neoplastic tissues from breast cancer patients." (PMID 25078270, 2014). "We showed that E2 induces export of S1P via ABCC1 and ABCG2 transporters, which may contribute to the nongenomic signaling of E2 important for breast cancer pathophysiology." (PMID 28912626, 2017).
lung carcinoma (46 papers, 2011 to 2025). "High levels of ABCC1 mRNA has been linked with resistance to vincristine, etoposide and cisplatin in human lung carcinoma cell lines." (PMID 25268163, 2014). "Compared with the wild A/A genotype, ABCB1 rs3842 A/G or G/G (OR 1.36, 95% CI 1.06–1.76) and ABCC1 rs212090 A/T or T/T (OR 1.37, 95% CI 1.03–1.83) genotypes were associated with an increased risk of lung cancer." (PMID 24212786, 2011). "In addition, circ_PVT1 makes lung cancer cells less responsive to Pemetrexed and cisplatin by elevating the expression of ABCC1 (also known as multidrug resistance-associated protein 1, MRP1)." (PMID 35055115, 2022). "Several ABC transporters are linked to lung cancer, such as ABCC1, ABCC3, ABCA3 and ABCC5." (PMID 24625834, 2014). "Telmisartan (7a)significantly inhibited the SP phenotype of ABCG2+ MCF-7 breast cancerand ABCC1+ A549 lung cancer cells, but only modestly affected ABCB1+A2780 V SP and IGROV-1 SP ovarian and PC3-DR and DU145-DR prostatecancer cells." (PMID 39693499, 2025). "Mechanistically, ABCC1 was targeted by miR-185-5p and negatively regulated its expression in lung cancer cells." (PMID 35444536, 2022). "CircPVT1 harbored miR-145-5p to regulate the expression of ABCC1 in chemotherapy-resistant lung cancer." (PMID 34140036, 2021). "ATP Binding Cassette transporter C1 (ABCC1, formerly MRP1) overexpression was reported to be associated with increased tumour size, differentiation and invasion in breast, liver and lung cancer." (PMID 32718079, 2020). "It is reported that the high expression levels of ABCC1 in various tumours such as lung cancer, oesophageal cancer and colorectal cancer lead to resistance to a variety of anticancer drugs." (PMID 32916774, 2020). "The contribution of ABCC1 biology in response to cigarette smoke exposure and to the associated development of COPD and lung carcinoma is intriguing." (PMID 30655622, 2019). "ABCC1 encodes ABC transporter MRP1, which was identified in a multidrug resistant lung cancer cell line in 1992." (PMID 28881788, 2017). "Multidrug resistance protein 1 (MRP1) or ABCC1 is a 190 kDa membrane-bound protein and was identified in 1992 in a multidrug resistant lung cancer cell line." (PMID 29061939, 2015). "Researchers have discovered that common polymorphisms of ABCB1 and ABCC1 can influence metabolism and disposition of the well-established carcinogen, NNK, and potentially increase the lung cancer risk." (PMID 23762359, 2013). "ABCA4, ABCC1, and ABCC showed significant associations with lung cancer susceptibility (P-values<0.0005)." (PMID 23762359, 2013). "To further elucidate the relationship between the major drug transporters and the resistance to paclitaxel, we measured the expression of ABCB1 and ABCC1 in lung cancer cell lines by quantitative real-time RT-PCR." (PMID 22179563, 2012). "For example, ABCC1 is highly expressed in lung cancer tissues." (PMID 34012960, 2021). "ABCC1 overexpression, also known as a multidrug resistance-associated protein-1 (MRP1), plays a crucial role in the failure of chemotherapy in a number of malignant tumors, including prostate, breast, and lung cancers." (PMID 34680470, 2021). "Among these, multidrug resistance-associated protein 1 (MRP1), also known as ABCC1, was first identified from drug-resistant lung cancer cells that did not express ABCB1 (MDR1 or P-glycoprotein)." (PMID 30486290, 2018). "Multidrug resistance-associated protein MRP1 (ABCC1) was the first of the xenobiotic-transporting MRP-related proteins to be cloned and was identified based on its overexpression in a multidrug-resistant lung cancer cell line." (PMID 26180516, 2015). "We performed a correlation analysis between NCAPG2 and 13 lung cancer stemness markers using the TCGA database and found that NCAPG2 was highly correlated with ABCC1, MYC, and EPCAM." (PMID 36139554, 2022).
lung carcinoma (continued). "An altered methylation pattern was detected in the promoters of ABCB1, ABCC1, and ABCG2 in breast and lung cancer, whereas the defective activity of histone acetylases including EP300, CBP, and PCAF was reported to be implicated in ABCB1 overexpression." (PMID 35205642, 2022). "ABCC1 was also described as a pro-ferroptotic gene through its capacity to generate GSH efflux and promote ferroptosis sensitivity in lung cancer cells." (PMID 35803910, 2022). "MDR1 and ABCC1 were considered to be the two most important drug-resistance-related proteins in DDP-resistance across diverse cancers, including lung cancer, colorectal cancer and gastric cancer." (PMID 33714198, 2021). "Meanwhile, we found a similar decrease of drug-resistant genes (ABCB1, ABCC1, and ABCG2) in lung cancer spheroids after apatinib treatment, which was further confirmed in CDDP-resistant A549 cells." (PMID 33980809, 2021). "Although there are inconsistencies in the literature, previous reports also support a link between genetic variations in the ABCC1 and ABCC2 genes, altered irinotecan pharmacokinetics and clinical outcomes in colon and lung cancer patients." (PMID 29066969, 2017). "Our previous observations on lung cancer cells NCI-H460 overexpressing ABC transporter proteins (LRP, ABCB1, BCRP, ABCC1 ABCC2 and ABCC3) confirmed the ability of resveratrol lignans to overcome the resistance to PTX." (PMID 27304668, 2016). "Several reports have shown the expression of high levels of ABCC1 and ABCC3 in lung cancer specimens." (PMID 27649127, 2016). "The multidrug resistance-associated protein 1 (MRP1), known as ABCC1, was first recognized in lung cancer cells that had no expression of ABCB1 (MDR1 or P-gp)." (PMID 32380783, 2020). "Our in vitro model of cigarette smoke extract conditioned media induction of ABCC1 gene expression may be valuable in further interrogating this biology and the functional consequences in the context of COPD and lung carcinomas." (PMID 30655622, 2019). "ABCC1 (also known as MRP1), another member of the ABC transporter family, is also of high importance as a cancer cell resistance mechanism and was identified in a doxorubicin-adapted subline of the lung cancer cell line H69." (PMID 35582596, 2019). "We proceeded to further test our hypothesis using two other ABCC1 expressing cell lines, the doxorubicin-resistant H69AR lung cancer cell line, and an ABCC1-transfected cell line (HEK293MRP1)." (PMID 29615646, 2018). "The next ground-breaking step came in 1992, when S.P. Cole published her studies showing that another ABC protein (later known as ABCC1) was responsible for chemotherapeutic agent resistance in the doxorubicin-selected lung cancer cell line H69AR, which does not express P-gp." (PMID 29401721, 2018).
ovarian carcinoma (32 papers, 2013 to 2025). A malignant neoplasm originating from the surface ovarian epithelium. "MDR-associated protein 1 (MRP1 or ABCC1) is involved in drug resistance in breast, lung and ovarian cancers and neuroblastoma." (PMID 33918653, 2021). "An experiment using a human ovarian carcinoma cell line reported that cannabinol inhibited the efflux transporter multidrug resistance-associated protein 1 (MRP1 or ABCC1)." (PMID 32601103, 2020). "Additionally, study found that increased levels of glycosylation-defective ABCC1 are associated with resistance to platinum compounds in ovarian carcinoma cells." (PMID 40083919, 2025). "A previous study examining crocin derived from saffron (Crocus sativus L.)plant in cisplatin-resistant ovarian cancer cells (A2780/RCIS) demonstrated a strong inhibitory effect on the mRNA expression of ABCC1 and ABCC2." (PMID 41303640, 2025). "Previous research has also demonstrated the importance of genetic variations in the ABCC1 gene, linking it to ovarian cancer, COPD, and major depression." (PMID 40225935, 2024). "Another study has shown that ABCC1 is a predictive marker of chemotherapy response in epithelial ovarian cancer." (PMID 38509620, 2024). "Blockade of miR-508-3p or upregulation of ABCC1 impaired the effects of circSETDB1 depletion on cell resistance to PTX in ovarian cancer." (PMID 38152652, 2023). "Previous studies showed that plant cannabinoids inhibited ABCC1 in ovarian cancer cells, and CBD exhibited the highest inhibition effects." (PMID 38100640, 2023). "Silencing of MALAT1 accelerated cisplatin sensitivity in ovarian cancer by suppression of the Notch1 pathway and ABCC1 expression." (PMID 36105363, 2022). "LINC01118 plays an oncogenic role in promotion of paclitaxel resistance via modulation of miR-134 and upregulation of ABCC1 in ovarian cancer cells." (PMID 36105363, 2022). "In ovarian cancer cells that were overexpressing ABCC1, CBD treatments boosted the intracellular accumulation of two ABCC1 substrates, Vincristine and Fluo3." (PMID 36297340, 2022). "Based on these results, it was revealed that in ascites-derived human ovarian cancer cells, ABCC1 and ABCG2 promote drug efflux." (PMID 36551731, 2022). "For instance, overexpression of multidrug resistance-associated protein 1 (MRP1), a unidirectional efflux transporter also known as ABCC1, is associated with decreased drug accumulation and increased resistance in ovarian cancer cells." (PMID 34336673, 2021). "ABCC1 has previously been linked to GPR55 in a feedback loop, where ABCC1 exports LPI, which binds to and activates GPR55, leading to downstream signaling, and this was implicated as important for prostate and ovarian cancer cell proliferation." (PMID 33081264, 2020). "In ovarian cancer cells over-expressing ABCC1, CBD exposure was able to increase the intracellular accumulation of 2 ABCC1 substrates, Fluo3 and Vincristine." (PMID 32708138, 2020). "THC was able to increase the accumulation of Fluo3 and Vincristine in ovarian cancer cells that over-expressed ABCC1, both of which are substrates for the transporter." (PMID 32708138, 2020). "Across multiple studies, positive immunohistochemical staining for ABCC1 (MRP1) has been seen in 22–68% of paraffin sections from ovarian cancers (for review." (PMID 28674494, 2017). "Moreover, circSETDB1 targeted miR-508-3p and increased the expression of ABCC1 (ATP-binding cassette subfamily C member 1) in ovarian cancer cells." (PMID 38152652, 2023). "However, high expression of ABCC1 also plays a role in disease progression and drug resistance in ovarian cancer." (PMID 36551731, 2022). "Similarly, increased expression of ABCC1 transcripts was found in ovarian cancer tissue before chemotherapy treatment compared to normal (healthy) ovarian tissue." (PMID 36551731, 2022).